PDX1 (pancreatic and duodenal homeobox 1)
Diseases named in the same sentence as PDX1 in open-access papers (continued):
Sharing a sentence is not in itself a finding about the gene and the disease.
Hyperglycemia (102 papers, 2010 to 2025). An increased concentration of glucose in the blood. "The mutation of Pdx1 resulted in hyperglycemia and a significant reduction in pancreatic cell mass, including a complete loss of endocrine cells, although it did not lead to a lethal phenotype." (PMID 39958891, 2025). "The pdx1 gene encodes a transcription factor essential for pancreatic β-cell development, and its loss leads to hyperglycemia and diabetic complications including nephropathy." (PMID 41516155, 2025). "VEGF and NO inhibitors and hypoglycemic agents alleviate the vascular changes caused by hyperglycemia, but the higher mortality of pdx1−/− mutants limits their use in adulthood." (PMID 36982274, 2023). "The control animals developed progressive hyperglycemia and an associated loss of PDx-1 and insulin mRNAs and diminution of glucose-stimulated insulin secretion." (PMID 36834496, 2023). "Targeted removal of Pdx1 from beta cells led to severe hyperglycemia in PKO mice associated with reprogramming of majority of Pdx1-deleted beta cells into alpha-like cells including de-repression of MafB transcription factor specific for alpha cells." (PMID 36246880, 2022). "Pdx1 levels are reduced in human islets from T2D donors and compromised Pdx1 expression in beta-cells is tightly linked to hyperglycemia and loss of cellular identity." (PMID 34436455, 2021). "Using the pdx1 diabetic zebrafish model, we now characterized the neuronal injuries caused by prolonged hyperglycemia and defined retinal cell-type specific responses." (PMID 34831487, 2021). "When body has hyperglycemia, it leads to increase the association of Pdx1 with p300 HAT, which involved in the enhancement the histone acetylation and insulin transcription." (PMID 32815547, 2020). "For instance, HbA1c has been shown to correlate positively with DNA methylation of INS and PDX-1 in human pancreatic islets and hyperglycaemia was associated with increased DNA methylation of the same genes in clonal β cells cultured in vitro." (PMID 23879380, 2013). "In these models, murine specific PDX-1 knockdown was associated with mild temporal hyperglycemia due to suppression of in situ islet PDX-1 expression and related islet hormones, as well as enhanced islet apoptosis." (PMID 22905092, 2012). "In a separate study, using an inducible REST transgene under the control of the Pdx1 promoter, we also observed postnatal beta cell loss leading to hyperglycemia (unpublished data)." (PMID 23029270, 2012). "Both hyperglycemia and elevated blood pressure have been associated with a worse recovery after stroke, which might explain the link between methylation at PDX1 gene and poor stroke outcome in our study." (PMID 38845005, 2024). "Notably, pancreas-specific knockout Mafa mice are glucose intolerant but have normal fasting glucose levels, whereas loss of PDX1 from pancreatic β cells causes overt hyperglycemia in different models." (PMID 36899442, 2023). "Homozygous mutations in the PDX1 gene and other mutations that impair the functionality of the PDX1 protein during embryonic development cause pancreas agenesis in mice and humans and eventually lead to fatal perinatal hyperglycemia." (PMID 36589234, 2022). "HasterpKO mice showed normal morphology and growth, yet male mice displayed glucose intolerance with insulin deficiency by 8 weeks, as well as fasting hyperglycaemia (glycaemia = 137 ± 16 mM in HasterpKO, 87 ± 5 mM in Hasterf/f littermates and 98 ± 4 mM in Pdx1-Cre; t-test P < 0.05)." (PMID 36202974, 2022). "Therefore, the downregulated PDX-1 and associated reduced SLC2a2 expression are coupled with hyperglycemia tolerance of β-cells." (PMID 36248064, 2022). "Thus, chronic hyperglycemia in β-cells increases oxidative stress and causes β-cell dysfunction due to decreased MafA and Pdx-1." (PMID 33918379, 2021).
Hyperglycemia (continued). "Downregulation of FOXO1 may be caused by chronic hyperglycemia‐induced oxidative stress; consequently, β‐cell fate cannot be maintained, due to insufficient β‐cell transcription factors, PDX1, MAFA, and NKX6.1, all of which are FOXO1‐dependent." (PMID 33312555, 2020). "The current study demonstrates that chronic hyperglycemia not only increased the SP formation but also triggered tau hyperphosphorylation and synapse loss in the brain, thus potentiating the cognitive dysfunction in the Pdx1+/−/APP/PS1 mice." (PMID 27406855, 2016). "The marked effects of the loss of a single Pdx1 allele on the progressive development of glucose intolerance and impaired glucose-stimulated insulin secretion indicate that Pdx1+/− mice may be a reasonable hyperglycemia model for analyzing AD pathogenesis." (PMID 27406855, 2016). "Among these, so-called “resistant” β-cells maintain high INS, MAFA, and PDX1 expression under diabetic conditions, preserving function despite hyperglycemia and inflammation." (PMID 41584842, 2025). "In mice, a homozygous deletion of the second exon of Pdx1 results in the failure of pancreatic development and death within a few days after birth due to hyperglycemia." (PMID 39958891, 2025). "The pdx1 mutant develops hyperglycemia and early DKD features, such as glomerular hypertrophy and impaired filtration barrier function, which leads to microalbuminuria." (PMID 41516155, 2025). "Research reported that in adult pancreatic β-cells, short-term hyperglycemia enhanced the binding of PDX1 to the insulin gene, thereby increasing insulin mRNA levels." (PMID 40405977, 2025). "To provide functional validation of TNFRSF1A dysregulation across species and confirm that its upregulation occurs in the context of hyperglycemia-induced kidney injury, we employed a zebrafish pdx1 knockdown model." (PMID 41516155, 2025). "All these features make the pdx1 mutant uniquely suitable among zebrafish models for studying the long‐term effects of hyperglycaemia." (PMID 38279951, 2024). "It has been shown in mouse models that homozygous deletion of this gene leads to pancreatic agenesis, while heterozygous mutations, such as in patients with PDX1/IPF1 MODY, lead to impaired insulin production and hyperglycemia." (PMID 39408828, 2024). "Among these, HIPK2 activity has been found to be affected by hyperglycemia conditions and also influences the activity of PDX-1." (PMID 38326874, 2024). "Rat studies demonstrated that beta cells decrease their expression of beta cell transcription factors Pdx1, Pax6, and Nkx6-1 and increase expression of ‘disallowed’ genes like Ldha and Hk1 in response to partial pancreatectomy and resultant hyperglycemia." (PMID 38904049, 2024). "Pdx1−/− mutants showed impaired pancreatic development and hyperglycemia, as well as dilated blood vessels and increased permeability in larvae." (PMID 36982274, 2023). "Here, we report that upregulation of PDX1 is related to miR-223-3p mimic injection under hyperglycemia conditions." (PMID 36869348, 2023). "Chronic hyperglycemia in pancreatectomized rats impairs β-cell differentiation, as indicated by reduced β-cell markers, such as Pdx1 and Nkx 6.155." (PMID 37524865, 2023). "One molecular mechanism of action through which chronic hyperglycemia can cause worsening β‐cell function is via decreased protein expression of Pdx1, whereas the positive effects of glucose on insulin transcription may be a result of its enhancement of Pdx1 nuclear translocation." (PMID 37568265, 2023). "One study found that knockdown of Pdx1 by antisense morpholino (MO) technology induced hyperglycemia in zebrafish, which resulted in pronephric glomerular dilatation and high atrophy of the filtration barrier." (PMID 36982274, 2023). "For example, pancreatic acinar cells overexpressing Ngn3, Pdx1, and Mafa simultaneously transdifferentiate into functional β-cells, which can reduce hyperglycemia in streptozotocin (STZ)-treated mice." (PMID 37524865, 2023).
Hyperglycemia (continued). "Reduced PDX-1 activity stimulates hyperglycemia and β-cell dysfunction and apoptosis, which is correlated to SLC2a2 and GCK down-expression." (PMID 36248064, 2022). "As explained later, activation of PKB inactivates FOXO and stimulates insulin gene expression, but in chronic hyperglycemia and oxidative stress, this pathway is weakened in β-cells and PDX1 and then insulin gene expression is reduced." (PMID 36109786, 2022). "Adult zebrafish develop organ complications following prolonged diabetic conditions, with the pdx1 zebrafish mutant being a novel model organism showing hyperglycemia-induced activation of retinal angiogenesis." (PMID 35840638, 2022). "They found that the massive expression of PDX-1 promoted the expression of the insulin gene, which resulted in the amelioration of hyperglycemia symptoms in diabetic model mice." (PMID 36551213, 2022). "Pdx1 knockdown or knockout in zebrafish induces hyperglycemia and is accompanied by organ alterations similar to clinical diabetic retinopathy and diabetic nephropathy." (PMID 35840638, 2022). "In contrast, β-cell-specific removal of PDX-1 resulted in pancreatic agenesis and severe hyperglycemia." (PMID 36551213, 2022). "Conditional deletion of pdx1 in the developing β cells in rodents results in hyperglycemia, reduced number of β cells and an increased number of α cells." (PMID 34882233, 2021). "Here we have analyzed injury responses to chronic hyperglycemia in the neural retina of the zebrafish diabetic pdx1 mutant." (PMID 34831487, 2021). "In the genetic pdx1 mutant diabetic zebrafish, hyperglycemia is maintained from larval stages through adulthood, enabling long-term studies." (PMID 34831487, 2021). "The pdx1 mutant diabetic zebrafish genetically resembles human neonatal diabetes in that homozygous mutants show early onset, persistent hyperglycemia, along with reduced insulin and reduced β-cells." (PMID 34831487, 2021). "The β-cell transcription factor Pdx1 has been shown to induce pancreatic transdifferentiation of liver tissue when delivered using adenoviral vectors and some improvement in hyperglycaemia when delivered to a humanized mouse model using an AAV2 vector." (PMID 33023100, 2020). "Contrary to the enhanced activity of PDX1 upon acute glucose increase, chronic exposure to hyperglycemia resulted in the downregulation of PDX1 mRNA and protein in HIT-15 cells, an insulin reporter-expressing cell line derived from hamster islet cells." (PMID 32394191, 2020). "Pancreatic β-cell malfunction is characterized by the lack of insulin production and secretion to regulate glucose metabolism, which results in hyperglycemia in PDX-1 knockout mice and IRS-2 knockout mice." (PMID 31627434, 2019). "Adenoviral delivery of Ngn3, Pdx1 and MafA in vivo has been shown to reprogram acinar cells and other cells of the gastrointestinal tract into β-like cells that can ameliorate hyperglycaemia in an experimental animal model of diabetes." (PMID 30337647, 2018). "It has been shown that hyperglycemia in zebrafish embryos, established by a morpholino mediated Pdx1 knockdown, resulted in an enlargement of the pronephric glomeruli, impairment of the pronephric filtration barrier, and defection of podocyte development." (PMID 28925940, 2017). "Our data obtained from cross-mated Pdx1+/−/APP/PS1 animals clearly demonstrated the effect of chronic hyperglycemia on AD pathology." (PMID 27406855, 2016). "An unexpected observation in the present study was that chronic hyperglycemia increased the GSK3 phosphorylation levels in the Pdx1+/− mouse brains compared with the WT mouse brains." (PMID 27406855, 2016). "Taken together, our results indicate that chronic hyperglycemia participates in enhanced Aβ deposition through increased Aβ production and suppressed Aβ clearance in Pdx1+/−/APP/PS1 mice." (PMID 27406855, 2016).
Hyperglycemia (continued). "To determine the responsiveness of the hyperglycemia in pdx1 mutants to pharmacological glucose modulators, we treated 5 dpf mutant larvae with increasing concentrations of the sulfonylurea drug tolbutamide." (PMID 26384018, 2015). "Here, we showed that coexpression of Pdx1, Ngn3, and MafA in primary hepatocytes induced hepatocytes-to-IPCs reprogramming and reversal of hyperglycemia in diabetic animals by using multicistronic vectors via liposome." (PMID 25006589, 2014). "Hyperglycemia recurred within 24 hours of graft removal and the histological analysis of the retrieved grafts revealed presence of Pdx1-, Nkx6.1- and C-peptide-positive cells." (PMID 23671681, 2013). "It is thus very likely that additional β-cell like cells needed were generated from the FoxA2 and/or Pdx1-positive fraction in vivo to eventually correct the hyperglycemia." (PMID 23671681, 2013). "Hyperglycemia was reverted in diabetic mice only when AAV-mediated transfer of Pdx-1 and Ngn-3 was combined with co-administration of an irrelevant adenoviral vector." (PMID 23110179, 2012). "Remarkably, systemic bi-shRNAmousePDX-1 and shRNAmousePDX-1 lipoplexes result in temporal hyperglycemia, representing a predictable off-target effect on mouse islets, since PDX-1 is the predominant regulator of insulin expression." (PMID 22905092, 2012). "Human BMSCs expressing VEGF and PDX1 reversed hyperglycemia in more than half of the diabetic mice and induced overall improved survival and weight maintenance in all mice." (PMID 22879915, 2012). "In other studies, transplantation of hTERT-FH-B fetal liver cells modified by Pdx1, was successful in correcting hyperglycemia in mice." (PMID 20504287, 2010). "Notably, the pdx1 zebrafish model develops diabetic kidney injury through hyperglycemia-dependent mechanisms, making it a physiologically relevant model for studying DKD pathogenesis." (PMID 41516155, 2025). "The high degree of pancreatic tissue damage observed in the diabetic control group, despite the elevated PDX1 expression, may be attributed to the severity of tissue damage caused by STZ, oxidative stress and hyperglycaemia." (PMID 39238175, 2024). "β-cell-specific removal of PDX1 results in severe hyperglycemia within days." (PMID 38674024, 2024). "It has been shown that chronic hyperglycemia gradually decreases insulin biosynthesis and secretion which is accompanied by reduced expression of very important insulin gene transcription factors MafA and PDX-1." (PMID 37720599, 2023). "Chronic hyperglycemia gradually decreases insulin biosynthesis and secretion which is accompanied by reduced expression of very important insulin gene transcription factors MafA and PDX-1." (PMID 37720599, 2023). "However, histopathological results showed that despite its high expression in the DC group, PDX1 is unable to perform significant tissue repair, most likely due to the severity of tissue damage caused by STZ, oxidative stress and hyperglycemia." (PMID 36109786, 2022). "Interestingly, mice with area IV mutations exhibited sexually dimorphic phenotypes: affected diabetic males with reduced PDX1 levels manifested hyperglycemia at weaning time versus phenotypically normal females." (PMID 36589234, 2022). "Furthermore, the homozygous pdx1 mutant is the first animal model to show retinal angiogenesis under hyperglycaemia." (PMID 34070439, 2021). "Ectopic PDX1 expression in adult human liver cells induced the development of functional insulin-producing cells; these cells when transplanted under the renal capsule of diabetic, immunodeficient mice ameliorated hyperglycemia." (PMID 34882233, 2021). "Also, In vivo recombinant-adenovirus-mediated gene transfer of pdx1 into liver cells ameliorated hyperglycemia in diabetic mice treated with streptozotocin." (PMID 34882233, 2021).
Hyperglycemia (continued). "Furthermore, adding an ACE inhibitor to the β-cell line improved the hyperglycemia-induced decrease in Ins1 and Pdx-1 expression, and suppressed the expression of Ngn3, endocrine progenitor cell marker, and Oct4, stem-like cell marker." (PMID 33918379, 2021). "However, another study described an increase in retinal layer thickness in a model of immersion-induced hyperglycaemia, and it has even been shown that, in the pdx1 model, there is an increase in nuclei in the inner nuclear layer." (PMID 34070439, 2021). "However, a combination of the three transcription factors, ngn3, MafA and pdx1, converted the acinar cells into beta-like cells and improved hyperglycemia in toxin-induced-diabetic mice." (PMID 34882233, 2021). "Hyperglycemia leads to increased DNA methylation at Pdx1 and INS in β cell." (PMID 32815547, 2020). "Thus, analyses of pdx1 morphants investigate effects of hyperglycemia on organ development, but long-term effects of hyperglycemia on organs, similar to diabetic late complications, should be addressed in pdx1 mutants." (PMID 28925940, 2017). "In zebrafish, the induction of hyperglycemia by injection of a pdx1 morpholino takes only two days." (PMID 28925940, 2017). "Importantly, the Pdx1+/−/APP/PS1 mice exhibited worse hyperglycemia with age, and their serum insulin levels were significantly lower than those of the original APP/PS1 mice (p < 0.05 or p < 0.01)." (PMID 27406855, 2016). "Here, our findings indicated that ERK1/2, JNK and P38 MAPK signaling were activated in the Pdx1+/− mouse brains, and this activation may represent an important molecular mechanism responsible for chronic hyperglycemia." (PMID 27406855, 2016). "Previous research has suggested that stable expression of PDX-1 in adult human mesodermal tissues activated expression of all four islet hormones including insulin and reversed hyperglycemia in vivo, but more factors that stimulate cells further toward differentiated normal β-cells were needed." (PMID 22761608, 2012). "Finally, it was shown that adenoviral vector-mediated co-expression of Pdx-1, Ngn-3, and Maf-A in the exocrine portion of the pancreas restored β-cell function and ameliorated hyperglycemia in adult mice." (PMID 23110179, 2012). "Under diabetic conditions, hyperglycemia per se and subsequent induction of oxidative stress decrease insulin biosynthesis and secretion, accompanied by reduction in expression and/or activities of insulin gene transcription factors PDX-1 and MafA." (PMID 23202973, 2012). "To gain mechanistic insights into whether OC could restore pancreatic gene expression of insulin and PDX1 under conditions of hyperglycemia, we further examined the gene expression of FOXO1, PDX1 and insulin in β-cells cultured with OC, with or without the AKT inhibitor." (PMID 40585255, 2025). "We could furthermore determine that pharmacologic Gck activation ameliorates hyperglycemia in pdx1 diabetic mutants without causing stress in endocrine β-cells or liver." (PMID 39580550, 2024). "Absence of Pdx1 during murine and human development, for example, leads to complete pancreatic agenesis, while beta cell specific Pdx1 depletion in adult mice results in loss of insulin expression, downregulation of MafA, and rapid onset hyperglycemia." (PMID 38904049, 2024). "However, PDX-1 and insulin levels decrease under the cytotoxic effect of long-term hyperglycemia." (PMID 36551213, 2022). "Moreover, hyperglycemia and elevated levels of FFAs also induce an increase in the transcriptional factor pancreatic and duodenal homeobox 1 (PDX1), which, in turn, increases the transcription of MALAT1 and can induce β-cell dysfunction through the PDX1/MALAT1/PTBP1 pathway." (PMID 34298896, 2021). "Expression of several β-cell (Pdx-1, MafA, Nkx6.1 and Glut2) and α-cell (Arx, Pax6 and MafB) markers was examined to determine whether the molecular identity of islet cells was altered by exposure to chronic hyperglycaemia." (PMID 25145789, 2014).